NF1 (neurofibromin 1)
Diseases named in the same sentence as NF1 in open-access papers (continued):
Sharing a sentence is not in itself a finding about the gene and the disease.
pheochromocytoma (continued). "Consistent with our earlier findings, LOH occurred in chromosomal regions spanning across Nf1, and this pattern of chromosomal loss was present in all three major tumor histologies arising from our mouse models (carcinoma, sarcoma and pheochromocytoma)." (PMID 26000738, 2015). "Ret initially appeared an especially attractive candidate suppressor, because activating RET and inactivating NF1 mutations can both lead to human pheochromocytoma, and because Drosophila Ret is expressed in larval brain neurons that resemble neuroendocrine cells." (PMID 24278035, 2013). "NF1 may be associated with other tumors of the central nervous system, including optic glioma, glioblastoma, and meningioma, and rarely with pheochromocytoma." (PMID 22747746, 2012). "A previous report suggested that gastrointestinal involvement in NF1 occurs as intestinal ganglioneuromas, GISTs, and carcinoids of the periampullary region of the duodenum that may be associated with pheochromocytoma." (PMID 16042772, 2005). "Additionally, NF1 can cause vascular abnormalities, skeletal dysplasia (such as scoliosis and tibial dysplasia), cognitive impairment, and hypertension due to renal artery stenosis or pheochromocytomas." (PMID 40568288, 2025). "Moreover, recent studies indicate that up to 25% of pheochromocytoma patients have a genetic background (NF1, VHL, SDHD, SDHB or RET gene mutations) and thus both the patients and their closest blood relatives require wide multidisciplinary diagnostics as well as long-term follow-up." (PMID 31137898, 2019). "Interestingly, somatic NF1 mutations are common in sporadic phaeochromocytomas." (PMID 25520849, 2014). "This case highlights hypoglycemia as a rare and atypical presentation of pheochromocytoma, particularly in patients with NF1." (PMID 40376359, 2025). "Despite not having a definitive diagnosis in this case, the incidental detection of an adrenal mass in a patient with known NF1 highlights the consideration of a pheochromocytoma or sympathetic paraganglioma in the differential." (PMID 41141169, 2025). "This case underscores the necessity for clinicians to maintain a high index of suspicion for pheochromocytoma in patients with NF-1 and hypertensive symptoms to enable timely intervention and prevent severe complications." (PMID 40741550, 2025). "NF-1 is an autosomal dominant disorder that infrequently presents with pheochromocytoma, a potentially life-threatening endocrine tumor." (PMID 40741550, 2025). "We reported an unusual presentation of pheochromocytoma with persistent hypoglycemia in a patient with NF1." (PMID 40376359, 2025). "In the context of pheochromocytoma, tumor development is believed to result from biallelic inactivation of the NF1 gene in chromaffin cells, leading to unchecked Ras/MAPK pathway activation and cellular proliferation." (PMID 40741550, 2025). "Everolimus, an mTOR inhibitor, has shown some efficacy in reducing lesion size in a subset of pheochromocytomas such as NF1 patients." (PMID 40649858, 2025). "In this case report, a 50-year-old woman with NF1 is described who presented with a right adrenal mass subsequently diagnosed as pheochromocytoma." (PMID 40741550, 2025). "These new genetic markers, along with the susceptibility genes like RET, NF1, VHL, SDH, and fumarate hydratase, are expanding our understanding of the genetic basis of pheochromocytoma." (PMID 40649858, 2025). "These mutations are linked to hereditary syndromes like VHL, NF1, and MEN2 and can lead to tumors in multiple tissues, including pheochromocytomas and paragangliomas." (PMID 40649858, 2025). "In humans, tumors in this kinase-driven cluster often include pheochromocytomas and paragangliomas associated with multiple endocrine neoplasia type 2 (MEN2) and neurofibromatosis type 1 (NF1)." (PMID 39591360, 2024).
pheochromocytoma (continued). "In our study, genetic counseling was provided to patients with hereditary pheochromocytomas, and the genetic results confirmed the presence of vHL, NF‐1, and MEN2A." (PMID 38747189, 2024). "The second cluster is defined by a kinase signature, including genes like RET (rearranged during transfection), NF1 (neurofibromin 1), and TMEM127 (a gene that encodes a membrane protein, mutations that are associated with pheochromocytomas." (PMID 39591360, 2024). "Of the 12 familial cases of pheochromocytoma, 9 were associated with MEN 2, 2 with NF1 and 1 with MAX pathological variants." (PMID 36896586, 2023). "Renovascular hypertension and pheochromocytoma should be screened in patients with NF-1 and hypertension." (PMID 37417633, 2023). "AMH can be sporadic or familial, resulting from germline mutations of genes known to cause pheochromocytoma, such as the RET gene in multiple endocrine neoplasia type 2 (MEN2) syndrome, or in the NF1, SDHB, and MAX genes." (PMID 36896586, 2023). "The concurrence of pheochromocytoma and MTC among the familial AMH cases supports a genetic association between familial pheochromocytoma and MTC with RET, SDHD, MAX, and NF1 pathological variants being reported." (PMID 36896586, 2023). "As pheochromocytoma is also common in those with NF-1, appropriate medical management followed by surgical resection was performed." (PMID 35251852, 2022). "The aim of this review is to summarize current knowledge on endocrine glands tumors associated with VHL, NF1, TSC, and CS, especially neuroendocrine tumors and pheochromocytomas/paragangliomas." (PMID 34025587, 2021). "Few data are currently available on adrenal-sparing surgery and NF1-associated PPGL, possibly because bilateral pheochromocytomas are present in a minority of patients." (PMID 34025587, 2021). "Compared with the general population, patients with NF1 in our study had significantly higher rates of pheochromocytoma (OR, 126; 95% CI, 81-195; P < .0001) and NET (OR, 14.1; 95% CI, 7.3-21.1; P < .0001)." (PMID 33734413, 2021). "Mutations in VHL, RET, NF1, SDHB, and SDHD account for 90% of all pheochromocytomas and paragangliomas." (PMID 32266384, 2020). "We further assessed the COX-2 status of a commonly used preclinical model of mouse pheochromocytoma (MPC) cells with heterozygous Nf1 knockout." (PMID 31142060, 2019). "Others have reported ATRX mutations in 12.6% of pheochromocytomas/paragangliomas, mostly associated with SDH alterations, but also in one tumor with an NF1 mutation." (PMID 31462295, 2019). "In accordance with the observations in clinical PPGL samples, COX-2 immunoreactivity was also high in spheroids and subcutaneous allografts derived from mouse pheochromocytoma (MPC) cells with a heterozygous Nf1 knockout." (PMID 31142060, 2019). "Gene expression microarray profiling showed that these tumors clustered with NF1-, RET,- and HRAS-mutated pheochromocytomas, indicating activation of the MAPK and PI3K-AKT signal transduction pathways." (PMID 29159601, 2018). "VHL, RET, NF1, SDHB, and SDHD are major susceptibility genes, accounting for 90% of familial pheochromocytomas/paragangliomas, whereas TMEM127, SDHA, SDHC, SDHAF2, and MAX are minor susceptibility genes responsible for 10% of these tumors." (PMID 30456751, 2018). "For the group of NF1-related tumors with much lower penetrance: low-grade pilocytic astrocytomas, low-grade gastrointestinal stromal tumors (GISTs), and most pheochromocytomas are rarely malignant in people with NF1." (PMID 30479396, 2018). "In particular, as the mTOR protein represents an important target of the RAS pathway; therefore its unregulated activation is typical of NF1-mutant paragangliomas/pheochromocytomas." (PMID 28187001, 2017). "These regions have also been shown to be affected in RET, NF1 and sporadic paragangliomas/pheochromocytomas, indicating the potential presence of driver genes on these autosomes." (PMID 28099933, 2017).
pheochromocytoma (continued). "The transcription profile of TMEM127-mutant pheochromocytomas was found to be similar to that of tumors with mutations in the RET and NF1 genes." (PMID 28187001, 2017). "The probability of pheochromocytomas in patients with mutant NF1 is approximately 0.1–5.7% whereas that of paragangliomas is very low." (PMID 28187001, 2017). "Transcription analysis showed these tumors to be similar to RET- and NF1-mutant pheochromocytomas and paragangliomas." (PMID 28187001, 2017). "On the other hand, some researchers also used a newly established mouse pheochromocytoma cell line from heterozygous NF1 gene knockout mice." (PMID 27990160, 2016). "The extent of LOH on chromosome 11 was similar between carcinomas, sarcomas, and pheochromocytomas arising in Nf1 mutant mice." (PMID 26000738, 2015). "In 2006, a study comprising a larger number of patients with pheochromocytoma/paraganglioma showed that 33% of the patients carried germline mutations in one of the following genes: VHL, RET, NF1, SDHB, and SDHD." (PMID 24899893, 2014). "Quantities of susceptibility genes mutation, including RET, SDHB, and NF-1, have been recognized as being possible to the development of AMH to pheochromocytoma." (PMID 25246937, 2014). "There are many complications of NF-1, including chronic hypertension, pheochromocytomas, brain tumors, malignant peripheral nerve tumors, and a high incidence of learning disabilities." (PMID 21569290, 2011). "Herein, we present a case of a patient with NF-1 and pheochromocytoma, who was successfully treated with laparoscopic right adrenalectomy 11 years ago." (PMID 20219130, 2010). "Pheochromocytoma occurs in 0.1%-5.7% of patients with NF-1, and in 20%-50% of NF-1 patients with hypertension, compared to 0.1% of all hypertensive individuals." (PMID 20219130, 2010). "To evaluate the link between hypoxia and Warburg effect, we studied mitochondrial electron transport, angiogenesis and glycolysis in pheochromocytomas induced by germ-line mutations in VHL, RET, NF1 and SDH genes." (PMID 19763184, 2009). "Unlike sporadic pheochromocytomas, NF1-associated pheochromocytomas are typically benign and less likely to be metastatic." (PMID 40741550, 2025). "The susceptibility to pheochromocytoma can be linked to germline pathogenic variants in the RET proto-oncogene and tumor suppressor genes such as von Hippel-Lindau (VHL), and Neurofibromatosis type 1 (NF1)." (PMID 39735644, 2024). "In this case, it was difficult to diagnose whether the spinal tumor originated from NF1 or was a pheochromocytoma metastasis." (PMID 38966763, 2024). "The major mutations associated with pheochromocytoma are von Hippel-Lindau gene (VHL), REarranged during Transfection (RET) proto-oncogene, neurofibromatosis type 1 gene (NF1), genes encoding four succinate dehydrogenase complex subunits (SDHx; i.e., SDHA, SDHB, SDHC, and SDHD genes)." (PMID 35932074, 2022). "Interestingly, the p.Arg1276* mutation in the GAP-related domain (GRD) was already reported in one patient with NF1 and pheochromocytoma." (PMID 35885913, 2022). "Additionally, individuals with NF1 occasionally develop pheochromocytomas and leukemias, most commonly myeloid leukemia and juvenile myelomonocytic leukemia (JMML), all of which are driven by aberrant RAS activity." (PMID 35188187, 2022). "Furthermore, uncontrolled activation of the RAS/RAF/ERK pathway is observed in paragangliomas/pheochromocytomas with mutations in the RET and NF1 genes." (PMID 28187001, 2017). "Previous reports in humans, based on gene expression profiling and unsupervised hierarchical clustering, demonstrate a tight association between pheochromocytomas with VHL and SDH mutations, which distinguishes them from pheochromocytomas with MEN2, RET, and NF1 mutations." (PMID 24465590, 2014). "Because pheochromocytoma occurs in 0.1 to 5.7% of patients with NF1." (PMID 20438631, 2010).
pheochromocytoma (continued). "A recent genome-wide expression study of phaeochromocytomas identified two distinct clusters: one containing SDH- and VHL-associated phaeochromocytomas and another containing MEN2- and NF1-associated phaeochromocytomas, while both clusters contained sporadic cases." (PMID 19432956, 2009). "However, within the realm of NF1, pheochromocytomas are much more frequent than paragangliomas." (PMID 41141169, 2025). "Nf1 knockout mice are not viable, and unlike humans, Nf1+/- mice do not develop any of the cardinal features of NF1 patients although they undergo loss of heterozygosity in other tissues to yield other NF1-related tumors such as pheochromocytomas." (PMID 38900740, 2024). "However, sporadic cases of 11 pheochromocytomas were reported and most associated with NF1, unlike our patient." (PMID 36922517, 2023). "However, as in our case, association of composite tumor with NF1 or MEN 2A had not been reported in the 4 cases of retroperitoneal composite pheochromocytoma/paraganglioma." (PMID 23587063, 2013). "The frequency of pheochromocytoma is 10–20% in VHL, 50% in MEN2, and 3% in NF1, with bilateral adrenal pheochromocytomas being the most common." (PMID 40649858, 2025). "Pheochromocytomas have the potential to be part of inherited syndromes such as MEN-2, VHL, and NF1, which implicate a variety of other pathologies and necessitate genetic screening of affected individuals and their family members." (PMID 39735644, 2024). "The heterozygous Nf1 +/-mouse provided the ‘MPC’ (mouse pheochromocytoma) line, derived from a pheochromocytoma in the mouse." (PMID 34957538, 2021). "Patients with these diseases are also predisposed to developing multiple endocrine tissue tumors, e.g., pheochromocytomas/paragangliomas are frequent in VHL and NF1." (PMID 34025587, 2021). "Here we present a case report of a male adult patient with triple malignancy (pheochromocytoma, GISTs of the small intestine and ampullary NET) as a first incidental manifestation of NF1." (PMID 31301733, 2019). "Methoxytyramine, one of the O-methylated metabolites of catecholamines, was used to discriminate different hereditary forms of pheochromocytoma, which indicated that patients with MEN2 and NF1 genes presented with tumors characterized by increased plasma concentrations of metanephrine." (PMID 31340453, 2019). "In contrast, none of the other rare NF1-associated tumors demonstrated ALT, including gastrointestinal stromal tumors (GIST), pheochromocytomas, glomus tumors, juvenile xanthogranulomas, and duodenal neuroendocrine tumors." (PMID 31462295, 2019). "Mice with complete absence of functional NF1 develop pheochromocytomas with high penetrance and exhibit higher expression levels of many genes including RET, which is responsible for early development of the central and peripheral nervous systems." (PMID 28187001, 2017). "A few studies reported somatic NF1 aberrations or inactivation in 26-41% of sporadic phaeochromocytomas from individuals without NF1." (PMID 25026295, 2014). "Hypertension is not rare in patients with NF-1 (with a prevalence of 16–19% in children), no matter whether it is the essential form or secondary to renal or aortic vasculopathy, or pheochromocytoma." (PMID 34988040, 2021). "Additionally, it is important to evaluate for the presence of Von–Hippel Lindau disease (VHL), neurofibromatosis-1(NF-1), and rearranged during transfection (RET) in cases of suspected pheochromocytomas and succinate dehydrogenase complex subunits (SDHD, SDHB, SDHC) gene mutations in paragangliomas." (PMID 33194923, 2020). "Pheochromocytomas in MEN2, VHL, and NF1 disorders usually are not the first clinical manifestation and are more likely to be benign and bilateral." (PMID 22953071, 2012). "No other NF1 related tumor (GIST, NET or pheochromocytoma) was diagnosed." (PMID 38874808, 2024).
RASopathies (100 papers, 2013 to 2026). "NF1 pertains to a range of several monogenic syndromes, currently classed together as the RASopathies, caused by germline mutations in genes encoding (rat sarcoma/mitogen-activated protein kinase) Ras/MAPK pathway components." (PMID 41540280, 2026). "Specific RASopathy-associated genes were intentionally excluded, notably NF1 (HGNC:7765) and SPRED1 (HGNC:20249)." (PMID 40496714, 2025). "Out of 48 cases with RASopathy-causing mutations, 14 were NF1 and have been described in a separate publication by the authors." (PMID 41292581, 2025). "The frequent association of NF-NS with missense and in-frame PVs in the NF1 gene, as well as the rare but significant co-occurrence of RASopathy PVs, underscores the importance of systematic RASopathy variant testing and genetic screening in this population." (PMID 40289159, 2025). "Although the NF1 gene is classified as a RASopathy‐associated gene, the prenatal phenotypic manifestations of NF1 variants remain poorly characterized." (PMID 41317105, 2025). "Specifically, NF1 and other somatic RASopathy‐associated mutations have been defined as ‘driver’ mutations in 12% of all MM and are present in 45% of MM that are wild type for BRAF and NRAS." (PMID 39355740, 2024). "While irritability scores were similar between the Rasopathies groups, we demonstrated different influences of NS and NF1 status on the associations between irritability and ADHD symptoms and social skills impairments." (PMID 39764141, 2024). "In this investigation, genomic ascertainment of two population-based, exome-sequenced, HER-linked cohorts were used to quantify Bonferroni-corrected risk of cancers arising from adults harboring P/LP germline variants in non-NF1 RASopathy genes." (PMID 39802765, 2024). "NF1 belongs to a list of various monogenic syndromes, currently grouped together as the RASopathies.These monogenic syndromes are caused by germline mutations in genes that encode components of the Ras/mitogen-activated protein kinase (RAS-MAPK) pathway." (PMID 38739321, 2024). "Upstream RASopathy variants in the NF1, SHP2 (encoded by Ptpn11) and RAS proteins have been shown to modulate PI3K/Akt, PKC and/or Rho/ROCK activity, in addition to the ERK1/2 pathway." (PMID 38826084, 2024). "Tumors with mutations in NF1 and constitutive activation of RASopathy genes are expected to be associated with a higher mutational load and, consequently, a greater probability of generating neoantigens." (PMID 36900152, 2023). "As neurofibromin regulates the Ras/MAPK pathway, NF1 is included among the RASopathies, a group of developmental disorders caused by germline mutations in genes encoding components of the Ras/MAPK pathway." (PMID 37081086, 2023). "Alberto Broniscer, MD, reported preliminary results of a multi‐institutional study addressing the association of CNS cancers with non‐NF1 RASopathies." (PMID 35266292, 2022). "NF1 belongs to a class of congenital anomaly syndromes called RASopathies, a group of rare genetic conditions caused by mutations in the Ras/mitogen-activated protein kinase pathway." (PMID 33530415, 2021). "The increase of GFAP immunoreactivity in the cortex is supported by previous reports that loss of the RASopathy gene NF1 results in a robust increase in GFAP expression in reactive astrocytes." (PMID 34222248, 2021). "The most frequent RASopathy, neurofibromatosis type I (occurrence 1: 3000), is caused by mutations of the NF1 tumor suppressor gene, which in mice was also linked to neural stem cell hyperproliferation." (PMID 33544116, 2021). "NF1 belongs to a class of congenital anomaly syndromes called RASopathies, a group of rare genetic conditions caused by mutations in the Ras/mitogen-activated protein kinase (RAS/MAPK) pathway." (PMID 33530415, 2021).